CGAS (cyclic GMP-AMP synthase)
Diseases named in the same sentence as CGAS in open-access papers (continued):
Sharing a sentence is not in itself a finding about the gene and the disease.
tumor (continued). "Disparity A represents the difference in ISRE reporter activity between THP1‐Lucia ISG cells treated with 2′3′‐cGAMP and those treated with combined 2′3′‐cGAMP, exosomes, and STF‐1623, which indicates the enhancement effect of tumor‐derived exosome assisted 2′3′‐cGAMP on the cGAS‐STING pathway." (PMID 38498770, 2024). "Notably, the prolonged high content of manganese ions in the tumor maintained the activated condition of cGAS-STING pathway." (PMID 38831378, 2024). "Additionally, tumor cells can spontaneously take up mtDNA from the TME, promoting tumor survival by activating the cGAS-STING pathway." (PMID 39464890, 2024). "After the onset of tumors, the cGAS-STING pathway plays a crucial role in tumor clearance." (PMID 38523155, 2024). "However, it is regrettable that few studies focus on the autonomous functions of the cGAS-STING pathway in specific cell types at different stages of tumor development." (PMID 38523155, 2024). "However, the key to the transformation of the antitumor role of the cGAS‐STING pathway into a pro‐tumor effect is still unclear." (PMID 38145335, 2024). "Previous studies have shown that RT can disrupt the DNA structure of tumor cells, resulting in a large number of DNA fragments in their cytoplasm, which activates the cGAS-STING pathway, thereby causing the release of IFN-I and inducing a stronger anti-tumor immune response." (PMID 38431575, 2024). "Interestingly, loss of ENPP1 function suppressed metastasis, restored immune infiltration in the tumor microenvironment, and synergized with immune checkpoint inhibition in a cGAS-STING-dependent manner." (PMID 38095464, 2024). "Depletion of NK cells showed minimal antitumor effects, whereas the depletion of CD4+ or CD8+ T cells resulted in a significant decrease in both tumor growth inhibition and survival benefit, suggesting that T cells play a critical role in cGAS-initiated immunotherapy." (PMID 38518087, 2024). "To validate our hypothesis, we initially established a tumor model with both cGAS and NF-κB p65 abnormalities." (PMID 38782895, 2024). "Contributions of PTEN to tumour immunity through the cytosolic cGAS-STING pathway may provide new insights into the treatment of PTEN loss tumours." (PMID 38214828, 2024). "cGAS-STING pathway not only inhibits tumor progression, but also promotes tumor progression." (PMID 38515746, 2024). "The cGAS–STING pathway is the key cytosolic DNA sensor responsible for the type I IFN production, DC activation, and subsequent priming of CD8+ T cells against tumor-associated antigens." (PMID 38168435, 2024). "cGAS also suppresses tumors by inducing autophagy and apoptosis in tumor cells." (PMID 40018367, 2024). "Other effects of radiation include the observation that irradiated mesenchymal stem cells can promote tumor metastasis in a mouse lung metastasis model, which could be blocked by knocking down the cGAS-STING pathway in the irradiated mesenchymal stem cells." (PMID 38659582, 2024). "The established role of the cGAS-STING pathway in promoting anti-tumor and anti-viral immunity has promoted the development of synthetic small molecule STING agonists that mimic the endogenous STING ligand cGAMP, several of which have entered clinical development (29, –, 32)." (PMID 38095464, 2024). "We next challenged Cgas−/− or WT mice with Cgas-proficient cells to address whether these tumor cGAS-mediated phenomenon are determined by host cGAS." (PMID 38177099, 2024). "Clinical data also indicate the anti-tumor function of the cGAS-STING pathway." (PMID 38523155, 2024). "Activation of the cGAS-STING pathway within tumor cells can play an anti-tumor role." (PMID 38523155, 2024). "Regarding downstream elements of TIM-3 on DCs, TIM-3 may prevent the cytoplasmic localization and activation of cGAS-STING on DCs, where the cGAS-STING pathway is fundamental for exerting anti-tumor immunity." (PMID 38791963, 2024).
tumor (continued). "Moreover, by multiple lines of evidence, we showed that N-MYC can suppress cGAS/STING signaling in tumor cells." (PMID 38748789, 2024). "cGAS is crucial to the tumor immune microenvironment in ESCC." (PMID 39050748, 2024). "Interestingly, GSDMD suppresses the cGAS-driven type I interferon response by depleting intracellular K+, and can, in this manner, promote tumor progression." (PMID 39224600, 2024). "This review illustrates all the various aspects related to possible improved immunotherapy, specifically addressing the stimulation of the cGAS/STING pathway as feasible pharmacological target for stimulating innate immunity as well as transforming the cold tumour phenotype." (PMID 39215193, 2024). "In summary, our findings demonstrate that OGT-mediated DNA damage and activate cGAS-STING pathway as an important tumor cell-intrinsic mechanism to repress antitumor immunity and provides a window for potential therapeutic opportunities for in OGT-dependent cancer." (PMID 38168435, 2024). "This review comprehensively explores the cGAS-STING pathway’s role in reconditioning the TME, detailing the underlying mechanisms of innate and adaptive immunity and highlighting the contributions of various immune cells to tumor immunity." (PMID 38817608, 2024). "They ascribed the tumor-suppressive effect to the capacity of F. nucleatum-derived succinic acid to interfere with the cGAS-IFN-β pathway, which is crucial in CD8+ T cell trafficking to the tumor microenvironment, consequently causing a reduction in the antitumor response." (PMID 38256554, 2024). "Whether immune cells are recipients of tumor-derived cGAMP or have their cGAS directly activated, both pathways result in activation of STING leading to downstream IRF3 signaling." (PMID 38659582, 2024). "CGAS-STING can cause the production of immunostimulatory factors such as IFN and activate a variety of immune cells, thus playing an important role in anti-tumor immunity." (PMID 39445027, 2024). "Additionally, in vivo experiments demonstrate that TMPyP4 enhances the anti-tumor immune response by triggering DNA damage and activating the cGAS-STING pathway, which fosters CD8+ T cell activation and dendritic cell maturation." (PMID 39528472, 2024). "However, by comparing disparities A and B, we observed that lower concentrations of exosomes exhibited negative regulation of cGAS‐STING signaling due to tumor exosomal ENPP1‐dominated hydrolysis of 2′3′‐cGAMP." (PMID 38498770, 2024). "Furthermore, we depleted tumor cGAS and employed STING inhibitor C-176 to block host STING activation." (PMID 38177099, 2024). "Drugs targeting this pathway may become more widely available, as evidence suggests that the cGAS-STING pathway is an excellent tumor target." (PMID 39464890, 2024). "Taken together, dMMR GC, as well as EBV (+) GC, exhibit high expression of tumor cell-intrinsic cGAS–STING, which might contribute to the immune-active TME through increased infiltration of CD8+ T cells." (PMID 39242811, 2024). "Consequently, damaged DNA in tumor cells and Mn2+ in the cytoplasm activated the cGAS-STING immune signaling pathway to evoke systemic anti-tumor immune response." (PMID 38724978, 2024). "Tumour cell-specific activation of cGAS/STING through accumulation of cytosolic dsDNA due to radiation-induced genomic instability of cancer cells may therefore prove advantageous compared to STING agonists." (PMID 39372406, 2024). "cGAS inhibition suppresses tumor growth and impairs DNA repair." (PMID 38145335, 2024). "In addition, DNA demethylase, TET2, modulates anti-tumor immunity by elevating cGAS levels in tumor cells." (PMID 39606248, 2024). "Interestingly, the cGAS-STING pathway can have contradictory impacts on tumor development even within the same cell type." (PMID 38523155, 2024).
tumor (continued). "Due to the continuous leakage of tumor cell DNA into the cytoplasm, the expression levels of genes in the cGAS–STING signaling pathway of tumor cells may be regulated, thus avoiding an antitumor immune response." (PMID 38525112, 2024). "Activation of cGAS-STING pathway may therefore restore tumor’s immune checkpoint responsiveness and further combination with anti-PD-1 treatment should bring beneficial therapeutic effect." (PMID 38832958, 2024). "Indeed, ENPP1‐OE EXOs showed a stronger capability to inhibit cGAS‐STING signaling than that of exosomes from WT tumor cells (inhibition rate 22.0% versus 12.4% in 24 h) due to the high expression of ENPP1." (PMID 38498770, 2024). "Therefore, ensuring the normal operation of the intrinsic cGAS-STING pathway in tumors is a necessary condition for it to exert its anti-tumor effects." (PMID 38523155, 2024). "In contrast, for the treatment of malignant tumors, STING agonists may be used to enhance the body’s anti-tumor immunity, agonists targeting cGAS are rare." (PMID 39445027, 2024). "The observations that 5-FU and oxaliplatin activate the cGAS/STING signaling pathway suggest that the anti-tumor effect of FOLFOX may be partially attributed to cGAS/STING-mediated immune activation." (PMID 39469633, 2024). "The mechanism of cGAS inhibiting chromosome fusion and promoting replicative senescence may be a vital breakthrough in tumor therapy." (PMID 38515746, 2024). "This is the first study to report the pro‐tumor effects of the cGAS‐STING pathway in PTCL." (PMID 38145335, 2024). "PRMT1 acts as a suppressor of tumor immune surveillance in a cGAS (cyclic GMP-AMP synthase)-dependent manner through methylating cGAS at the conserved R133 residue on its N-terminus, and then blocking cGAS DNA sensing signaling, thus promoting tumor immune evasion." (PMID 39201539, 2024). "Notably, the activation of the cGAS-STING signaling pathway assumes a pivotal role in tumor biotherapy." (PMID 39063990, 2024). "Therefore, cancer cells are the dominant source of cGAMP in the tumor microenvironment, especially when their cGAS expressions are upregulated by TET2 in this study." (PMID 38177099, 2024). "Indeed, blocking mitochondrial transfer from osteocytes to tumor cells—via MIROCKO—blocked an inflammatory cGAS-STING signature in tumor cells and decreased antitumor immune responses." (PMID 39128718, 2024). "A previous study reported that the activation of SENP3 in tumor cells could be coupled with the cGAS signaling, synergistically promoting host anti-tumor immune responses." (PMID 39314848, 2024). "Hence, both the tumor microenvironment and stage/grade-dependent expression of DNA-PKcs and cGAS need to be carefully considered when devising strategies to enhance tumor immunogenicity." (PMID 39043779, 2024). "Notably, this positive trend was attenuated upon the addition of STING inhibitors, underscoring the fact that this combination therapy induces anti-tumour immune effects by activating the cGAS/STING signalling pathway." (PMID 38816831, 2024). "However, activation of the cGAS–STING signaling pathway is dependent on the exposure of tumor cell DNA within the cytoplasm, and this process requires some consideration." (PMID 38525112, 2024). "The cGAS–STING signaling pathway also has a dual role in tumor metastasis." (PMID 39090094, 2024). "cGAS inhibition suppresses tumor growth and impaires DNA damage repair." (PMID 38145335, 2024). "To further examine whether cGAS hyperactivation directly contributes to the delayed tumor progression and increased T cell infiltration observed in Prmt3-KO tumors, we knocked down cGAS in Prmt3-KO Hepa1-6 cells." (PMID 39256398, 2024). "Although the cGAS-STING pathway evolved as a key host defense mechanism for sensing non-self pathogenic DNA molecules, it also plays a crucial role in inflammatory diseases, anti-tumor responses, and autoimmune pathologies (4, –, 6)." (PMID 38095464, 2024).
tumor (continued). "cGAS-STING is another immune response pathway activated in the tumor microenvironment by BCG." (PMID 38611044, 2024). "This study shows that circulating tumor cells, before dissemination from a primary tumor, are empowered to escape NK cell surveillance and form metastasis by cross‐talking with mesenchymal stromal cells in the tumor microenvironment via an intercellular cGAS‐cGAMP‐STING‐IFNβ‐HLA‐I signaling loop." (PMID 38638003, 2024). "To test whether host STING relies on tumor cGAS to regulate vascular normalization and anti-tumor immune response, we challenged Sting−/− mice and WT mice with Cgas-proficient cells or ctrl cells, respectively." (PMID 38177099, 2024). "Specifically, PARPi-induced cGAS-STING activation within BRCA1-deficient cancer cells results in the intratumoral production of IFN-I, subsequent immune cell infiltration, and T cell-dependent anti-tumor immunity." (PMID 38459088, 2024). "cGAS inhibits tumorigenesis and progression by promoting tumor cell senescence and clearance." (PMID 40018367, 2024). "The regulatory mechanism behind the up-regulation of the tumor cell-intrinsic cGAS–STING expression in dMMR GC, as well as EBV (+) GC, remains unknown." (PMID 39242811, 2024). "MMP NDs could induce tumor cell ferroptosis directly or through reducing the glutathione accumulated in tumor cells as well as activating the cGAS-STING pathway." (PMID 39125107, 2024). "As such, targeting LYPLAL1-mediated cGAS depalmitoylation may enhance cGAS activation, offering a potential strategy to boost anti-tumor immunotherapy efficacy." (PMID 40018367, 2024). "Similarly, the anti-tumor immunity triggered by ionizing radiation (IR) is dependent on the cGAS-STING pathway." (PMID 38473997, 2024). "We evaluated the antitumor effects of Schisandra chinensis lignan component Schisandrin C (SC) in 4T1 and MC38 tumor-bearing mice, and studied the enhancing effects of SC on the cGAS-STING pathway and antitumor immunity through RNA sequencing, qRT-PCR, and flow cytometry." (PMID 39170700, 2024). "Sensing of foreign DNA, including tumor DNA, is often mediated by the cGAS/STING pathway." (PMID 38896472, 2024). "In addition, manganese ions have been shown to inhibit tumor development by activating the cGAS-STING pathway, which in turn activates immunity." (PMID 38675217, 2024). "Colonic tumors in cGAS-deficient mice demonstrated higher ki67 and BrdU incorporation compared to WT mice as well as increased activation of STAT3, highlighting possible effects on tumor proliferation." (PMID 39050748, 2024). "Exosomes isolated from tumor cells consist of DNA that can activate immune cell responses via the STING/cGAS mechanism and pathway, which may control the internal immunity of the tumor through the process of checkpoint immunotherapy." (PMID 38683256, 2024). "In addition to its role in cancer cells, the cGAS-STING pathway can be activated in neighboring immune cells by dsDNA released from tumor cells, which primes DCs and subsequently activates CD8+ T cells." (PMID 39449023, 2024). "Finally, DNA derived from apoptotic cells, exosomal DNA, and transposable elements have also been shown to induce the activation of cGAS–STING signaling pathway in tumor cells." (PMID 38525112, 2024). "In addition to this, radiation therapy can also participate in anti-tumor activity by modulating the tumor microenvironment and promoting anti-tumor immune responses, one mechanism of which involves the excitation of the cGAS- STING pathway." (PMID 38817608, 2024). "Collectively, these data suggest that TREX1 depletion in chemoresistant SCLC cells contributes to the induction of a tumor intrinsic innate immune response by activating the cGAS-STING pathway, which senses chemotherapy-derived dsDNA aberrantly accumulated in the cytoplasm." (PMID 39177280, 2024). "Exploring whether extracellular cGAS/cGAMP signaling is particularly relevant in tumor cells with high genomic instability remains to be investigated." (PMID 39544936, 2024).
tumor (continued). "Combined with the previous research results, we speculate that it may be because smoking inhibits the DNA damage of tumor cells induced by platinum chemotherapy drugs, weakens the activity of cGAS-STING pathway and reduces the level of STING protein." (PMID 38425343, 2024). "However, DNA leaks into the cytoplasm abnormally in tumor cells, activating the cGAS–STING signaling pathway, ultimately inducing IFN‐I in DCs and endothelial cells to initiate antitumor immunity." (PMID 38525112, 2024). "For example, nuclear cGAS suppresses DNA repair and promotes tumour growth." (PMID 39183480, 2024). "The activation of cGAS-STING pathway in tumor cells can result in attenuated tumor growth, enhanced immunogenicity and susceptibility to lysis by tumor-infiltrating lymphocytes promoting tumor clearance." (PMID 39020402, 2024). "Targeting TREX1 might enhance the effectiveness of immunotherapies by increasing the immune system’s ability to recognize and destroy tumor cells through the activation of the cGAS-STING pathway." (PMID 38881902, 2024). "Furthermore, the released PTX, in synergy with Mn2+, alleviates tumor hypoxia, normalizes tumor vasculature, heightens the sensitivity of DNA sensors cGAS and STING, and promotes IFN production, thereby reinforcing the antitumor immune response of ICB." (PMID 38715912, 2024). "Indeed, most tumor-relevant type I IFNs are induced by cytosolic or endolysosomal sensing of nucleic acids, where DNA that has leaked from the nucleus or mitochondria of tumor cells can induce cGAS/STING signaling." (PMID 38912586, 2024). "When introducing STF‐1623 to the incubation process of 2′3′‐cGAMP and exosomes, although the ISRE reporter activity was enhanced, no activity change for control ADP was observed, which indicated that tumor exosomal ENPP1 inhibited cGAS‐STING pathway by hydrolyzing 2′3′‐cGAMP." (PMID 38498770, 2024). "The cGAS-STING pathway increases the immune system's anti-tumor response to RT." (PMID 38347787, 2024). "However, cGAS-STING activation-mediated chronic inflammation can also promote tumor metastasis through the induction of immunosuppressive TME." (PMID 38195584, 2024). "Therefore, effectively activating the cGAS-STING pathway within tumor cells emerges as a critical strategy to enhance the effectiveness of cancer treatment." (PMID 38512518, 2024). "Consequently, increasing the levels of DNA and Mn2+ in tumor cells to activate the cGAS-STING immune pathway holds significant potential for cancer immunotherapy." (PMID 38724978, 2024). "The cGAS-STING pathway activation in antigen-presenting cells (APCs) is an important mechanism of innate immune activation against the tumor, due to the activation of a cascade reaction through TBK1 and IRF3 phosphorylation, consequent transcription, and type I interferon production." (PMID 39684497, 2024). "For example, downregulation of TREX1 expression in tumor cells may elevate DNA accumulation, ribosomal collisions, and translational stress, thereby augmenting cGAS-dependent DNA recognition." (PMID 39420203, 2024). "Since RSK2 induced cGAS chromatin incorporation by phosphorylation at Ser120 and Thr130, we hypothesized that RSK2-cGAS signaling pathway might play an essential role in tumor promoter-induced cell transformation and cancer cell proliferation." (PMID 39424777, 2024). "Therefore, in the case of LL‐37‐2′3′‐cGAMP, tumor‐derived exosomes only inhibit the cGAS‐STING pathway by hydrolyzing LL‐37‐2′3′‐cGAMP through ENPP1." (PMID 38498770, 2024). "We review the available data on how ionizing radiation stimulates cGAS-STING signaling as well as how STING agonists may potentiate the anti-tumor immune response induced by ionizing radiation." (PMID 38659582, 2024). "However, in NP‐OVA/PS immunized mice, cGAS−/− mice exhibited significantly higher tumor volume and weight compared to the control group, accompanied by a significant reduction in survival rate." (PMID 38900071, 2024).